UBQLN1 (ubiquilin 1)
Description:
Plays an important role in the regulation of different protein degradation mechanisms and pathways including ubiquitin-proteasome system (UPS), autophagy and endoplasmic reticulum-associated protein degradation (ERAD) pathway. Mediates the proteasomal targeting of misfolded or accumulated proteins for degradation by binding (via UBA domain) to their polyubiquitin chains and by interacting (via ubiquitin-like domain) with the subunits of the proteasome. Plays a role in the ERAD pathway via its interaction with ER-localized proteins UBXN4, VCP and HERPUD1 and may form a link between the polyubiquitinated ERAD substrates and the proteasome. Involved in the regulation of macroautophagy and autophagosome formation; required for maturation of autophagy-related protein LC3 from the cytosolic form LC3-I to the membrane-bound form LC3-II and may assist in the maturation of autophagosomes to autolysosomes by mediating autophagosome-lysosome fusion. Negatively regulates the TICAM1/TRIF-dependent toll-like receptor signaling pathway by decreasing the abundance of TICAM1 via the autophagic pathway. Promotes the ubiquitination and lysosomal degradation of ORAI1, consequently down-regulating the ORAI1-mediated Ca2+ mobilization. Suppresses the maturation and proteasomal degradation of amyloid beta A4 protein (A4) by stimulating the lysine 63 (K63)-linked polyubiquitination. Delays the maturation of A4 by sequestering it in the Golgi apparatus and preventing its transport to the cell surface for subsequent processing (By similarity). Ubiquitinates BCL2L10 and thereby stabilizes protein abundance. [Isoform 1]: Plays a role in unfolded protein response (UPR) by attenuating the induction of UPR-inducible genes, DDTI3/CHOP, HSPA5 and PDIA2 during ER stress. Plays a key role in the regulation of the levels of PSEN1 by targeting its accumulation to aggresomes which may then be removed from cells by autophagocytosis. [Isoform 2]: Plays a role in unfolded protein response (UPR) by attenuating the induction of UPR-inducible genes, DDTI3/CHOP, HSPA5 and PDIA2 during ER stress. [Isoform 3]: Plays a role in unfolded protein response (UPR) by attenuating the induction of UPR-inducible genes, DDTI3/CHOP, HSPA5 and PDIA2 during ER stress. Plays a key role in the regulation of the levels of PSEN1 by targeting its accumulation to aggresomes which may then be removed from cells by autophagocytosis.
Synonyms: PLIC-1; DA41; DSK2; XDRP1; UBQN
Tractability: Antibody: UniProt places it where antibodies can reach, with high confidence; its Gene Ontology location is reachable by antibodies, with high confidence. PROTAC: UniProt records ubiquitination sites on it; ubiquitination databases record sites on it; its protein half-life has been measured.
Gene: Protein-coding gene on chromosome 9 (83,657,386 to 83,707,993, reverse strand). Ensembl gene ENSG00000135018.
Subcellular location: Cytoplasm; Nucleus; Endoplasmic reticulum; Cytoplasmic vesicle, autophagosome; Cell membrane
Subcellular location (Human Protein Atlas): Nucleoplasm; Cytosol
Pathways (Reactome):
Vesicle-mediated transport: Cargo recognition for clathrin-mediated endocytosis
Gene Ontology:
Molecular function: identical protein binding; kinase binding; polyubiquitin modification-dependent protein binding; protein binding
Biological process: aggrephagy; autophagosome assembly; autophagosome maturation; cellular response to hypoxia; ERAD pathway; macroautophagy; negative regulation of store-operated calcium channel activity; positive regulation of ERAD pathway; positive regulation of protein ubiquitination; regulation of oxidative stress-induced intrinsic apoptotic signaling pathway; regulation of protein ubiquitination; response to endoplasmic reticulum stress; regulation of macroautophagy; ubiquitin-dependent protein catabolic process; negative regulation of toll-like receptor 3 signaling pathway; negative regulation of transport
Cellular component: aggresome; autophagosome; cytoplasm; cytosol; endoplasmic reticulum; nucleoplasm; perinuclear region of cytoplasm; plasma membrane; protein-containing complex; nucleus
Genetic constraint (gnomAD): Loss-of-function variants: 12 observed, 54.42 expected, observed/expected ratio (o/e) 0.22, 90% interval 0.14 to 0.36. The upper end of that interval is the gene's LOEUF score, 0.36, which puts it in group 1 of 6, group 1 being the genes least tolerant of losing a copy. Missense variants: 491 observed, 658.18 expected, observed/expected ratio (o/e) 0.75, 90% interval 0.69 to 0.8. Synonymous variants: 233 observed, 234.34 expected, observed/expected ratio (o/e) 0.99, 90% interval 0.89 to 1.11.
Homologues: Orthologues: chimpanzee UBQLN1 (99% identical), macaque UBQLN1 (99% identical), guinea pig UBQLN1 (96% identical), dog UBQLN1 (95% identical), pig UBQLN1 (92% identical), rabbit UBQLN1 (90% identical), mouse Ubqln1 (88% identical), rat Ubqln1 (87% identical), tropical clawed frog ubqln1 (76% identical), Drosophila melanogaster Ubqn (49% identical), Caenorhabditis elegans ubql-1 (36% identical). Paralogues in human: UBQLN2 (80% identical), UBQLN4 (63% identical), UBQLN3 (48% identical), UBQLNL (28% identical), UBL7 (18% identical).
Diseases named in the same sentence as UBQLN1 in open-access papers:
UBQLN1 is named in the same sentence as 54 diseases in open-access papers, as found by Europe PMC text mining. Sharing a sentence is not in itself a finding about the gene and the disease. The quoted sentences say what the papers report.
Alzheimer disease (20 papers, 2007 to 2025). A progressive, neurodegenerative disease characterized by loss of function and death of nerve cells in several areas of the brain leading to loss of cognitive function such as memory and language. "Mitochondrial dysfunction and impaired import are also hallmarks of Alzheimer's disease, and mutations in the UBQLN1 “M” domain are considered risk factors for Alzheimer's disease." (PMID 40086734, 2025). "UBQLN1 genetic variants or dysfunction is linked to neurodegenerative diseases such as Alzheimer’s disease (AD)." (PMID 38902824, 2024). "For example, Ubiquilin 1 (UBQLN1) expression is associated with neuronal loss seen in Alzheimer’s disease, which is of interest as cognitive decline was observed in at least one patient with BET1‐related disease." (PMID 34779586, 2021). "UBQLN1 has been reported to be associated with Alzheimer’s disease, while UBQLN 2 has gained importance because of its association with amyotrophic lateral sclerosis and frontotemporal dementia (ALS/FTD) pathogenesis." (PMID 35082784, 2021). "Single-nucleotide polymorphisms in UBQLN1 were suggested to confer susceptibility to Alzheimer’s disease." (PMID 28463112, 2017). "A single nucleotide polymorphism in the pyrimidine tract of UBQLN1 intron 7 is associated with partial skipping of exon 8 and has recently been linked to an increased risk of Alzheimer's disease." (PMID 17579712, 2007). "Ubiquilin-1 and ubiquilin-2 both bind the proteasome and, interestingly, have both been linked to Alzheimer's disease, since they were proposed to bind presenilins and localize to Lewy bodies and neurofibrillar tangles." (PMID 18047733, 2007). "Mutations in UBQLN1 are associated with motor neuron diseases such as Alzheimer’s disease." (PMID 38902824, 2024). "Moreover, in humans, mutations in Ubqln1, 2 and 4 are strongly associated with the onset of neurodegenerative diseases such as dementia, Alzheimer’s disease and amyotrophic lateral sclerosis." (PMID 34650520, 2021). "Since the polymorphism UBQ-8i (rs12344615) in UBQLN1 has been associated with increased risk of late-onset Alzheimer’s disease (LOAD) and differences in UBQLN1 exon 8 splicing, we asked whether APP/UBQLN1 co-splicing was modulated by UBQ-8i." (PMID 30545302, 2018). "Moreover, genetic variations in the ubiquilin-1 gene are proposed to substantially increase the risk of developing Alzheimer's disease." (PMID 18047733, 2007). "Thus, in addition to their role in Alzheimer’s disease, polymorphisms in UBQLN1 may influence susceptibility to tuberculosis, analogous to the dual role of PARK2 (which encodes parkin) in Parkinson’s and leprosy." (PMID 26225865, 2015). "Also, a particular polymorphism in a UBQLN1 intron may increase the risk of suffering Alzheimer’s disease." (PMID 24674348, 2014). "In the recent ten years, UBQLN1 is found to participate in neurodegenerative disease development, such as Alzheimer’s disease (AD), by regulating the maturation of full-length amyloid precursor protein (APP)." (PMID 37463174, 2023). "For example, the genetic variance in UBQLN1 has been recognized as candidate genes for Alzheimer’s disease." (PMID 36238831, 2022). "UBQLN1 has been widely studied in neurodegenerative diseases and was found to be deregulated in various disorders ranging from Alzheimer’s disease to cancer." (PMID 34001851, 2021). "Additional results linking UBQLN1 with the quality control of Alzheimer’s disease-related proteins have been found recently." (PMID 24674348, 2014). "Brains of Alzheimer's disease (AD) patients often have a decreased level of ubiquilin-1 which may contribute to late-onset AD." (PMID 22518139, 2012). "Finally, reduced UBQLN1 levels were found in the brain cortex of Alzheimer’s disease patients." (PMID 24674348, 2014).
breast carcinoma (17 papers, 2017 to 2026). "Exosome miR-155 specifically targeted UBQLN1 in adipocytes, and the increased expression of UBQLN1 reversed the fat loss in adipocytes and the brown fat switch caused by the breast cancer-derived exosome." (PMID 38689293, 2024). "Conversely, overexpression of UBQLN1 was found to reverse exosome-induced adipose browning in mouse models of breast cancer cachexia." (PMID 41498391, 2026). "In breast cancer, miR-200c specifically targets Ubiquilin 1, inhibiting autophagy induced by radiotherapy." (PMID 39735677, 2025). "UBQLN1 is abnormally upregulated in breast cancer, and the knockdown of UBQLN1 inhibited the invasion and stemness of breast cancer cells through the AKT pathway." (PMID 37370699, 2023). "miR-200a and miR-200 c are both belong to the microRNA 200 family, miR-200 c has been shown to enhance radiosensitivity in breast cancer cells by targeting UBQLN1; miR-200 c also enhances radiosensitivity in lung cancer." (PMID 34903128, 2021). "The Ubqln1 gene is lost or under-expressed in many human cancer cell lines, and Ubqln1 was reported to be involved in many types of cancers, including breast cancer and lung cancer." (PMID 29899380, 2019). "In breast cancer cells, miR-200c suppressed ubiquilin-1 expression and enhanced radiation-induced autophagy." (PMID 29029445, 2017). "MiR-200c has been reported to inhibits autophagy and enhances radiosensitivity in breast cancer cells by targeting UBQLN1; meanwhile, miR-200c increases the radiosensitivity of non-small-cell lung cancer cell line A549 by targeting VEGF-VEGFR2 pathway." (PMID 29051585, 2017). "AURKA regulated pan-breast cancer-associated RNA splicing events including GOLGA4, RBM4 and UBQLN1." (PMID 37415951, 2023). "Indeed, knockdown of UBQLN1 enhances radio-sensitivity and breast cancer cell apoptosis by suppressing irradiation-induced autophagy and when UBQLN1 is re-introduced into the cells, the radio-sensitivity is eventually reversed." (PMID 32549375, 2020). "Therefore, Sun and co-workers demonstrated that miR-200c inhibits autophagy and enhances radio-sensitivity in breast cancer cells by targeting UBQLN1." (PMID 32549375, 2020). "Therefore, high UBQLN1 expression is considered to be a worse prognostic factor for patient with gastric cancer and a novel marker to predict poor prognosis in breast cancer." (PMID 32549375, 2020). "In addition, the inhibition of UBQLN1 reduced the invasion and cancer stemness of breast cancer." (PMID 35951366, 2022).
lung cancer (14 papers, 2014 to 2025). A malignant neoplasm involving the lung. "This study aims to investigate the expression of UBQLN1 in lung cancer (LC) tissue and the diagnostic capability of autoantibody to UBQLN1 (anti-UBQLN1) in the detection of LC and the discrimination of pulmonary nodules (PNs)." (PMID 38431566, 2024). "In the present study, we showed that the loss of UBQLN1 drives tumorigenesis and lung cancer metastasis, which was associated with an increase in MYC expression, cell cycle progression, and EMT." (PMID 37444499, 2023). "As our previous study has proved that it is very common to screen single biomarker with low sensitivity, the merit of anti-UBQLN1 is that it not only can diagnose high-risk lung cancer patients from healthy individuals but also can be a promising biomarker in the discrimination of pulmonary nodules." (PMID 38431566, 2024). "Loss of UBQLN1 promotes migration and epithelial-to-mesenchymal transition of lung cancer cells." (PMID 37415951, 2023). "Similarly, we found that decreased expression of UBQLN1, which was reduced in male BE-responsive patients, was associated with increased survival in male lung cancer patients." (PMID 33075110, 2020). "Previous studies from different groups have reported that UBQLN1 and UBQLN2 have been associated with various neurological disorders (Zeng); however, their cellular and biochemical roles in various cell types including lung cancer remain unexplored." (PMID 37444499, 2023). "Their previous studies reported that the loss of UBQLN proteins is associated with the progression of lung cancer, confirming that the low expression of UBQLN1 and UBQLN2 caused by miR-155 (as demonstrated by luciferase assays) promotes greater invasion and migration in lung cancer tumors." (PMID 38069307, 2023). "It has been reported that the deregulation of UBQLN1 and/or UBQLN2 is associated with various neurological disorders; however, their cellular and biochemical role in various cell types including lung cancer remain largely unexplored." (PMID 37444499, 2023). "Moreover, we reported that UBQLN1 is frequently lost and underexpressed in lung cancer cell lines as well as human lung adenocarcinomas." (PMID 37444499, 2023). "Finally, we analyzed the correlation between UBQLN1 expression and the survival of lung cancer patients through the online dataset." (PMID 34546848, 2021). "Interestingly, UBQLN1 proteins are frequently lost in lung cancer patients and the decreased UBQLN levels have proven to induce EMT in lung cancer cells." (PMID 32549375, 2020). "We identified UBQLN1 non-sense mutations in 31% (Q176*) and 53% (G499*) of variants reads from the TCGA and non-TCGA non-redundant breast and lung cancers studies, respectively." (PMID 32549375, 2020). "Ubiquilin 1 was found to be a promising biomarker for lung cancer with an AUC of over 0.7." (PMID 24755629, 2014). "However, little research is related to the resistance of lung cancer by targeting UBQLN1 until now." (PMID 38431566, 2024). "UBQLN1 expression was positively correlated with overall survival (OS) and post-progression survival (PPS) of lung cancer patients." (PMID 34546848, 2021). "Together our results most clearly highlighted the importance of TEK, LDB2, ATF6 and UBQLN1 in NSCLC patient BE responses, underscoring the value of examining system-level gene interactions in order to better understand the determinants of lung cancer patient therapeutic responsiveness." (PMID 33075110, 2020).
lung adenocarcinoma (6 papers, 2013 to 2024). A carcinoma that arises from the lung and is characterized by the presence of malignant glandular epithelial cells. "We further confirmed our findings of stabilization of MYC following the loss of UBQLN1 in additional lung adenocarcinoma cell lines PC9 and H358." (PMID 37444499, 2023). "Next, we performed immunofluorescence staining of MYC in lung adenocarcinoma cell lines following a loss of UBQLN1 or UBQLN2." (PMID 37444499, 2023). "We observed an increase in the expression of MYC following the loss of UBQLN1 or UBQLN2 in lung adenocarcinoma cell lines including A549, HOP62, H23, and H2009." (PMID 37444499, 2023). "Using lung adenocarcinoma cell lines, we observed an increase in cell viability, clonogenic potential, and cell migration following the loss of either UBQLN1 or UBQLN2, which was associated with an increase in MYC expression." (PMID 37444499, 2023). "We observed an increase in the expression of MYC following the loss of UBQLN1 in the lung adenocarcinoma cell line." (PMID 37444499, 2023). "Increased ubiquilin-1 protein, and decreased phosphorylated ubiquilin-1 have been found to be associated with lung adenocarcinoma, linking ubiquilin-1 function to cancer." (PMID 35401099, 2022). "These in vivo findings further confirmed that the loss of UBQLN1 drives EMT in lung adenocarcinoma." (PMID 37444499, 2023). "We observed an increase in cell viability and clonogenic potential following the loss of either UBQLN1 or UBQLN2 in lung adenocarcinoma cells, which we hypothesized was due, at least in part, to increased MYC expression." (PMID 37444499, 2023). "Interestingly, we observed that MYC was significantly upregulated following the loss of UBQLN1 in lung adenocarcinoma cell lines." (PMID 37444499, 2023). "Furthermore, consistent with lung adenocarcinoma cell lines, we also observed an increase in the expression of proteins involved in cell cycle progression including CyclinD3 and CyclinB1 following the loss of UBQLN1." (PMID 37444499, 2023). "UBQLN1 protein was overexpressed in lung adenocarcinoma (LUAD) tissues compared to para-tumor tissues." (PMID 38431566, 2024). "In the present study, we observed an increase in cell viability following the loss of UBQLN1 and UBQLN2 in lung adenocarcinoma cell lines, which was associated with a decrease in early apoptosis as revealed by annexin/7AAD staining." (PMID 37444499, 2023). "Immunofluorescence staining of MYC revealed a drastic increase in nuclear expression of MYC following the loss of UBQLN1 and/or UBQLN2 in lung adenocarcinoma cells." (PMID 37444499, 2023). "We performed a cell migration assay following a combined siRNA-mediated knockdown of either UBQLN1 or UBQLN2 with MYC in lung adenocarcinoma cell lines A549 and HOP62." (PMID 37444499, 2023). "In our study using lung adenocarcinoma cell lines, we observed an increase in the expression of MYC following the loss of either UBQLN1 and/or UBQLN2." (PMID 37444499, 2023). "The loss of UBQLN1 or UBQLN2 increases cell viability and clonogenic potential in lung adenocarcinoma cells H2030, H2009, and A549 cells." (PMID 37444499, 2023). "Since we observed an increase in cell proliferation following the loss of UBQLN1 and UBQLN2, we performed a clonogenic assay in lung adenocarcinoma cell lines following the loss of UQLN1 and UBQLN2." (PMID 37444499, 2023). "Immunofluorescence staining of MYC revealed a drastic increase in nuclear expression following the loss of UBQLN1 or UBQLN2, or a combined loss of both UBQLN1 and UBQLN2 in lung adenocarcinoma cells." (PMID 37444499, 2023). "In our study, involving lung adenocarcinoma cell lines, including A549 and HOP62, we observed that the loss of UBQLN1 and UBQLN2 increases cell migration." (PMID 37444499, 2023). "A few studies found that the level of UBQLN1 mRNA in lung adenocarcinoma was significantly higher than that in normal control." (PMID 34546848, 2021).